FAP (fibroblast activation protein alpha)
Diseases named in the same sentence as FAP in open-access papers (continued):
Sharing a sentence is not in itself a finding about the gene and the disease.
glioblastoma (continued). "It this work we investigated the effect of TGFbeta signaling on FAP expression in multiple cell types present in glioblastoma microenvironment." (PMID 33494271, 2021). "Previously, we demonstrated increased FAP expression in glioblastomas and described its localisation in cancer and stromal cells." (PMID 34282761, 2021). "Abundant FAP expression is also observed around abnormally proliferating blood vessels in the stroma of glioblastoma." (PMID 34490078, 2021). "We previously reported that FAP was most prominently upregulated in the mesenchymal subtype of glioblastoma based on the data from 173 glioblastomas in The Cancer Genome Atlas (TCGA) database." (PMID 33494271, 2021). "In tissue isolates from patients, FAP is most highly expressed in mesenchymal cells and in grade IV tumors, which demand therapeutic interventions distinct from other glioblastoma subtypes." (PMID 34931988, 2021). "These experiments revealed that TGFbeta-1 upregulates the expression of FAP in human permanent and non-stem glioma cell cultures, brain vascular pericytes, and glioblastoma-derived endothelial cells and FAP+ mesenchymal cells." (PMID 33494271, 2021). "Recently, we demonstrated an increased expression of FAP in glioblastomas, particularly those of the mesenchymal subtype." (PMID 33494271, 2021). "Nevertheless, approaches utilizing FAP expression for tumor imaging, including imaging of glioblastomas, and targeted delivery of anticancer therapeutics have been recently described." (PMID 33494271, 2021). "Human brain vascular pericytes (HBVP) and glioblastoma-derived FAP+ mesenchymal (pFAP) cell cultures displayed a marked upregulation of their FAP enzymatic activity after treatment with TGFbeta-1." (PMID 33494271, 2021). "By means of fluorescence immunohistochemistry and confocal microscopy, we detected TGFbeta-1 immunopositivity broadly in glioblastoma tissues including regions in the immediate vicinity of FAP-immunopositive perivascular stromal cells." (PMID 33494271, 2021). "We found that both FAP and TGFbeta-1 are upregulated in glioblastomas and display a significant positive correlation." (PMID 33494271, 2021). "In glioblastomas, the enzymatic activity of FAP displayed statistically significant positive correlation with FAP protein concentration." (PMID 33494271, 2021). "In comparison with the heterogeneity of expression observed on tumor cells, expression of FAP in the vascular compartment of glioblastoma was remarkably consistent." (PMID 33082953, 2020). "Microarray data from The Cancer Genome Atlas (TCGA) revealed a significant overexpression of FAP in glioblastoma compared to normal brain." (PMID 33082953, 2020). "Previous studies have also observed expression of FAP in glioblastoma cell lines and tissues, but the degree of intratumor heterogeneity has not been well defined." (PMID 33082953, 2020). "Single‐cell analyses of dissociated tumors facilitated a detailed characterisation of the main cellular components of the glioblastoma microenvironment and revealed that vessel‐localised FAP is because of expression on both ECs and pericytes." (PMID 33082953, 2020). "We validated a new target antigen for glioblastoma, fibroblast activation protein (FAP), by undertaking a detailed expression study of human samples." (PMID 33082953, 2020). "This was important to establish, considering that future FAP‐targeting immunotherapies for glioblastoma would likely be initially tested in the setting of recurrent disease following failure of standard therapies." (PMID 33082953, 2020). "This detailed analysis of the expression patterns of fibroblast activation protein (FAP) reveals it to be an important new target antigen for immunotherapy of glioblastoma." (PMID 33082953, 2020). "As FAP is also expressed by glioblastomas, these theranostics have potential for the diagnosis and treatment of pediatric cancers." (PMID 33330054, 2020).
glioblastoma (continued). "To further assess FAP expression in distinct areas of the glioblastoma microenvironment, we analysed the Ivy Glioblastoma Atlas transcriptomic dataset." (PMID 33082953, 2020). "We aimed for the first time to broadly assess the inter‐ and intratumor heterogeneity in FAP expression; to precisely define the cell types within tumors that express FAP; and to compare glioblastoma to healthy tissues." (PMID 33082953, 2020). "Together, our findings reveal FAP as a promising new target antigen for immunotherapy of glioblastoma, potentially allowing not only destruction of tumor cells but also effective elimination of their supporting vascular network." (PMID 33082953, 2020). "Our study in human glioblastoma reveals heterogeneous expression of FAP on tumor cells, coupled with near‐ubiquitous expression around blood vessels, with both ECs and pericytes contributing to the observed vascular expression." (PMID 33082953, 2020). "To obtain final proof that cell surface FAP is expressed by both ECs and pericytes in glioblastoma, we analysed dissociated glioblastoma tissue specimens (n = 8) using high‐parameter flow cytometry." (PMID 33082953, 2020). "In this study, we reveal FAP to be a potentially useful target antigen for novel glioblastoma immunotherapies." (PMID 33082953, 2020). "Here, we have undertaken a detailed analysis of the expression patterns of FAP in tumor and normal tissues to assess its suitability as a target antigen for immunotherapy of glioblastoma." (PMID 33082953, 2020). "FAP expression is observed in glioblastomas and can be a valuable theranostic target for pediatric cancers." (PMID 33330054, 2020). "The observation of FAP expression by ECs in glioblastoma raised the possibility that FAP is also expressed by blood vessels in other tissues." (PMID 33082953, 2020). "Together, these analyses reveal that FAP gene expression is elevated in glioblastoma compared to either normal brain or lower grade gliomas, with high levels of expression associated with poor survival." (PMID 33082953, 2020). "To address this question, and to more definitively identify the cell types in the glioblastoma microenvironment expressing FAP, we used single‐cell RNA sequencing (scRNAseq) analysis of dissociated tumor tissue." (PMID 33082953, 2020). "Immunostaining of tissue sections, flow cytometry and single‐cell RNA sequencing reveal broad expression of FAP by not only glioblastoma tumour cells but also endothelial cells and pericytes within the tumour microenvironment." (PMID 33082953, 2020). "To directly demonstrate FAP expression on pure populations of glioblastoma cells, we analysed a variety of cultured human cell types." (PMID 33082953, 2020). "We found that FAP was consistently overexpressed in a large proportion of patient tumors and patient‐derived glioblastoma cultures compared to normal tissue." (PMID 33082953, 2020). "Several lines of evidence in our study demonstrate that FAP is expressed by a subset of human glioblastoma tumor cells." (PMID 33082953, 2020). "FAP was expressed at the gene and protein level by a subset of glioblastoma tumor cells, and more broadly by the tumor vasculature." (PMID 33082953, 2020). "Thus, in addition to replicating the heterogeneous nature of glioblastoma tumors, a mixed U87/U251 tumor model also seems suitable to examine the bystander killing capacity of FAP‐CAR‐T cells in vivo." (PMID 38975278, 2024). "Rather, our detailed expression analyses of all cell types in glioblastoma revealed heterogeneous expression of FAP on the tumor cells, coupled with near‐ubiquitous expression around tumor blood vessels, with expression observed on both endothelial cells and pericytes." (PMID 38975278, 2024). "More recently, we have proposed FAP as a candidate immunotherapy target antigen for glioblastoma." (PMID 38975278, 2024). "PT100, a small molecule inhibitor of FAP, is a promising drug for glioblastoma." (PMID 36382346, 2023).
glioblastoma (continued). "That is, these cells may have a positive TGFβ-FAP autoregulatory loop, which was previously shown in a broad spectrum of cell types present in the glioblastoma microenvironment." (PMID 37509656, 2023). "The impact of FAP on glioblastoma metabolic and immune microenvironment becomes achievable." (PMID 36382346, 2023). "Based on these results, it is reasonable to speculate that the EMT process was involved in the invasion and migration of glioblastoma cells when FAP was knocked down or overexpressed." (PMID 36382346, 2023). "In addition, TGF-β1 has been shown to be involved in FAP transcription and can act as one of the regulators of the FAP promoter in the glioblastoma microenvironment." (PMID 37006278, 2023). "In our pilot study, 18 F-FAPI PET/CT detected 69.6% (16/23) of all lesions, which could be attributed to the varying FAP expressions in different molecular glioblastoma subtypes or the status of the blood-brain barrier." (PMID 36566187, 2022). "Some 65% of glioblastomas are FAP-positive intraparenchymally." (PMID 36566187, 2022). "FAP and FAP mRNA are overexpressed in most glioblastomas, especially in the mesenchymal subtype." (PMID 36566187, 2022). "Factors controlling FAP expression in glioblastomas are unknown, but evidence suggests that transforming growth factor beta (TGFbeta) can trigger mesenchymal changes in these tumors." (PMID 33494271, 2021). "Expression of FAP and all TGFbeta isoforms was highest in the mesenchymal subtype glioblastomas." (PMID 33494271, 2021). "Taken together, we identified a subpopulation of FAP+ mesenchymal cells in the perivascular niche in glioblastoma that may contribute to tumour progression by promoting angiogenesis and supporting dissemination of transformed cells into the surrounding tissue." (PMID 34282761, 2021). "Here, we investigated whether TGFbeta promotes FAP expression in transformed and stromal cells constituting the glioblastoma microenvironment." (PMID 33494271, 2021). "Interestingly, the FAP-immunopositive cells within the glioblastoma microenvironment were localized in the immediate vicinity of the TGFbeta-1 immunopositive stromal and cancer cells." (PMID 33494271, 2021). "Considering the important role of TGFbeta-1 signaling in glioblastoma progression, the TGFbeta-induced expression of FAP opens an interesting possibility of evaluating these approaches for parallel therapeutic targeting of several cell subpopulations in glioblastoma." (PMID 33494271, 2021). "Glioblastoma-derived endothelial cell (pEC) cultures showed a highly variable level of baseline FAP enzymatic activity but all exhibited a significantly upregulated FAP enzymatic activity after treatment with TGFbeta-1." (PMID 33494271, 2021). "Collectively, these data suggest that TGFbeta-1 may contribute to the regulation of FAP expression in the glioblastoma microenvironment." (PMID 33494271, 2021). "More recently, CD90 has been shown to drive glioblastoma cell invasion, suggesting that FAP might mark a particularly invasive subset of tumor cells." (PMID 33082953, 2020). "However, we noted with interest reports suggesting that, in glioblastoma, FAP can be expressed by the tumor cells themselves, as well as an unidentified stromal population within the tumor microenvironment." (PMID 33082953, 2020). "Therefore, expression of FAP appears to be a unique feature of angiogenic tumor blood vessels, compared to healthy vessels, and is particularly prominent in glioblastoma." (PMID 33082953, 2020). "Furthermore, analyses of the Ivy Glioblastoma dataset revealed intense expression of FAP in areas of microvascular proliferation and hyperplastic blood vessels selected by laser capture microdissection." (PMID 33082953, 2020). "Therefore, FAP is almost ubiquitously expressed in the immediate vicinity of glioblastoma tumor vessels." (PMID 33082953, 2020).
glioblastoma (continued). "However, previous studies have demonstrated a direct functional role for FAP in other cancer types, suggesting that this is an area worthy of future investigation in the context of glioblastoma." (PMID 33082953, 2020). "Within glioblastoma tissues, the strongest expression of FAP was around blood vessels." (PMID 33082953, 2020). "Although we did observe that high FAP expression is associated with reduced overall survival in the TCGA glioblastoma dataset, this does not necessarily indicate a functional role for FAP in disease progression." (PMID 33082953, 2020). "Moreover, we have used confocal microscopy, flow cytometry and single‐cell transcriptomics to demonstrate that FAP is expressed by multiple cell types in the glioblastoma microenvironment, with expression on ECs and pericytes as well as the tumor cells." (PMID 33082953, 2020). "For paediatric glioblastoma, the proportion of FAP‐expressing tumors (32.4%) was comparable to the adult disease, while pilocytic astrocytoma, a lower grade glioma, was characterised by a lower frequency of FAP‐expressing tumors (13.3%), again similar to adult low‐grade glioma." (PMID 33082953, 2020). "FAPα is also expressed in the membrane of BMSCs and another kind of MSCs, and FAPα expressed by stromal cells in tumor microenvironment promote MM cells and glioblastoma growth." (PMID 28881756, 2017). "FAPI-positive spots in glioblastomas may reflect tumour areas with increased invasiveness or epithelial to mesenchymal transition, as it has been demonstrated previously that overexpression of FAP contributes to these processes." (PMID 36077788, 2022). "Our results show that FAP+ mesenchymal cells promote angiogenesis and glioma cell migration and growth by paracrine communication and in this manner, they may thus contribute to glioblastoma progression." (PMID 34282761, 2021). "Which factors control FAP expression in glioblastomas is currently unknown." (PMID 33494271, 2021). "Our detailed analyses of FAP expression, including evidence of surface protein expression (using flow cytometry and immunofluorescence staining of nonpermeabilised cells), suggest that it meets the criteria for an excellent immunotherapy target in glioblastoma." (PMID 33082953, 2020). "We tested FAP‐CAR‐T cell function using model cell lines, tumor cells expanded from patient glioblastoma tissues, and a mouse model designed to recapitulate the natural heterogeneity of glioblastoma." (PMID 38975278, 2024). "On the other hand, FAP-specific PET imaging represented promising results for GTV contouring in head and neck cancer, nasopharyngeal carcinoma, adenoid cystic carcinoma, glioblastoma, and esophageal cancer." (PMID 35280710, 2022). "In this study, we show that FAP+ stromal cells are mostly localised in the vicinity of activated CD105+ endothelial cells and their quantity positively correlates with glioblastoma vascularisation." (PMID 34282761, 2021). "Glioblastoma tissues costained for CD31 and FAP were therefore also examined using high‐power confocal microscopy." (PMID 33082953, 2020). "To unambiguously quantify the proportion of tumor vessels expressing FAP in our own tissue samples, we performed immunofluorescence staining for FAP together with the EC marker CD31 on fresh‐frozen glioblastoma tissues from nine patients." (PMID 33082953, 2020). "To assess FAP expression at the protein level, we performed IHC on 30 formalin‐fixed paraffin‐embedded (FFPE) specimens from histologically confirmed glioblastoma tumors using affinity‐purified sheep antiserum." (PMID 33082953, 2020). "As target cells, the FAP‐expressing U87 human glioblastoma cell line was compared with the FAP‐negative glioblastoma cell line U251." (PMID 38975278, 2024). "Despite all these characteristics, until now FAP has never been tested as a target antigen for immunotherapeutic strategies in glioblastoma." (PMID 38975278, 2024).
glioblastoma (continued). "Therefore, various cell lines, including glioblastoma (A172, U-87 MG), prostate (PC-3 and LNCaP), breast (MDA-MB-231), pancreatic (Panc-89), lung (A549), and colorectal (HT-29) cancer, were screened for FAP-expression on the cell surface using flow cytometry." (PMID 38102692, 2023). "The levels of FAP protein and FAP enzymatic activity were substantially higher in glioblastomas than in non-tumorous pharmacoresistant epilepsy (PRE) brain tissues." (PMID 33494271, 2021). "Wedemonstrate for the first time that TGFbeta-1 induces expression of FAP in non-stem glioma cells, pericytes, and glioblastoma-derived endothelial and FAP+ mesenchymal cells, but not in glioma stem-like cells." (PMID 33494271, 2021). "We used biochemical and immunohistochemical methods to show that the expression of both FAP and TGFbeta-1 was upregulated in glioblastomas as compared to non-tumorous brain tissues." (PMID 33494271, 2021). "In summary, this IHC study confirms that FAP is broadly expressed in glioblastoma tissues but not at all in healthy brain." (PMID 33082953, 2020). "By setting a conservative threshold for expression based on the mean + 3 × SD of the normal tissue samples, 39.6% of glioblastoma tissues (216/548 specimens) expressed FAP above the threshold, whereas none (0/9) of the normal brain tissues did." (PMID 33082953, 2020). "Vessel‐localised expression of FAP in glioblastoma has been observed previously, but the identity of the FAP+ cells within this niche was not clear." (PMID 33082953, 2020). "Together, these studies suggest that FAP is not commonly expressed by blood vessels within healthy tissues or by normal ECs, but can be strongly and consistently induced on ECs within the glioblastoma microenvironment." (PMID 33082953, 2020). "Our results thus far demonstrate that, within the glioblastoma microenvironment, FAP can be expressed by not just the tumor cells, but also EC lining tumor blood vessels and a population of cells closely associated with the vessels." (PMID 33082953, 2020). "Our findings advance FAP as a leading candidate for clinical CAR‐T therapy of glioblastoma and highlight under‐recognised antigen nonspecific mechanisms that may contribute meaningfully to the antitumor activity of CAR‐T cells." (PMID 38975278, 2024). "In addition, FAP-specific positron emission tomography revealed increased tracer uptake in glioblastoma and high-grade mutant astrocytoma, without significant uptake in diffuse astrocytoma." (PMID 34490078, 2021). "However, CAR‐T cells targeting FAP have never been investigated as a therapy for glioblastoma." (PMID 38975278, 2024). "Additionally, although we demonstrated the effect of FAP on the process of epithelial‐mesenchymal transition and M2 macrophage polarization in glioblastoma, it is not clear what role FAP plays in those processes, and the detailed regulatory mechanism remains to be elucidated in future studies." (PMID 36382346, 2023). "To determine whether TGFbeta-1 may contribute to FAP upregulation in glioblastomas, we cultured several different cell types representing cellular components of glioblastoma microenvironment, with and without human recombinant TGFbeta-1 for 72 h, and measured FAP enzymatic activity." (PMID 33494271, 2021). "Indeed, our ongoing studies have demonstrated promising evidence of efficacy for FAP‐targeting CAR‐T cells in a mouse xenograft model of glioblastoma, even where intratumoral expression of FAP is heterogeneous, and a distinct lack of toxicity (manuscript in preparation)." (PMID 33082953, 2020). "FAP expression correlated with TGFB1 and TGFB3, but not TGFB2 in all glioblastomas and in the mesenchymal subtype." (PMID 33494271, 2021). "Finally, a low dose of intravenously administered FAP‐CAR‐T cells controlled, without overt toxicity, the growth of subcutaneous tumors created using a mixture of antigen‐negative and antigen‐positive glioblastoma cells." (PMID 38975278, 2024).
glioblastoma (continued). "In contrast to glioblastomas, PRE brain tissues did not exhibit FAP immunopositivity." (PMID 33494271, 2021).